TNS2 (tensin 2)
Description:
Tyrosine-protein phosphatase which regulates cell motility, proliferation and muscle-response to insulin. Phosphatase activity is mediated by binding to phosphatidylinositol-3,4,5-triphosphate (PtdIns(3,4,5)P3) via the SH2 domain. In muscles and under catabolic conditions, dephosphorylates IRS1 leading to its degradation and muscle atrophy. Negatively regulates PI3K-AKT pathway activation. Dephosphorylates nephrin NPHS1 in podocytes which regulates activity of the mTORC1 complex. Under normal glucose conditions, NPHS1 outcompetes IRS1 for binding to phosphatidylinositol 3-kinase (PI3K) which balances mTORC1 activity but high glucose conditions lead to up-regulation of TNS2, increased NPHS1 dephosphorylation and activation of mTORC1, contributing to podocyte hypertrophy and proteinuria. Required for correct podocyte morphology, podocyte-glomerular basement membrane interaction and integrity of the glomerular filtration barrier (By similarity). Enhances RHOA activation in the presence of DLC1. Plays a role in promoting DLC1-dependent remodeling of the extracellular matrix.
Synonyms: C1-TEN; KIAA1075; TENC1; C1TEN
Tractability: Antibody: UniProt places it where antibodies can reach, with high confidence; its Gene Ontology location is reachable by antibodies, with medium confidence. PROTAC: UniProt records ubiquitination sites on it; ubiquitination databases record sites on it.
Gene: Protein-coding gene on chromosome 12 (53,046,969 to 53,064,379, forward strand). Ensembl gene ENSG00000111077.
Subcellular location: Cell junction, focal adhesion; Cell membrane; Cytoplasm
Gene Ontology:
Molecular function: identical protein binding; kinase binding; protein binding; protein tyrosine phosphatase activity
Biological process: negative regulation of cell population proliferation; negative regulation of insulin receptor signaling pathway; peptidyl-tyrosine dephosphorylation
Cellular component: cytoplasm; focal adhesion; plasma membrane
Genetic constraint (gnomAD): Loss-of-function variants: 76 observed, 150.28 expected, observed/expected ratio (o/e) 0.51, 90% interval 0.42 to 0.61. The upper end of that interval is the gene's LOEUF score, 0.61, which puts it in group 2 of 6, group 1 being the genes least tolerant of losing a copy. Missense variants: 1,703 observed, 1,860.9 expected, observed/expected ratio (o/e) 0.92, 90% interval 0.88 to 0.95. Synonymous variants: 726 observed, 753.67 expected, observed/expected ratio (o/e) 0.96, 90% interval 0.91 to 1.02.
Homologues: Orthologues: chimpanzee TNS2 (98% identical), macaque TNS2 (98% identical), dog TNS2 (92% identical), guinea pig TNS2 (90% identical), mouse Tns2 (90% identical), pig TNS2 (89% identical), rat Tns2 (89% identical), Caenorhabditis elegans shc-2 (8% identical), Drosophila melanogaster PVRAP (7% identical), Drosophila melanogaster Egfrap (6% identical). Paralogues in human: TNS4 (16% identical).
Diseases named in the same sentence as TNS2 in open-access papers:
TNS2 is named in the same sentence as 46 diseases in open-access papers, as found by Europe PMC text mining. Sharing a sentence is not in itself a finding about the gene and the disease. The quoted sentences say what the papers report.
nephrotic syndrome (6 papers, 2018 to 2024). A collection of symptoms that include severe edema, proteinuria, and hypoalbuminemia; it is indicative of renal dysfunction. "The direct link of TNS2 to human nephrotic syndrome came from the identification of TNS2 mutations in four families with partially treatment-sensitive NS." (PMID 37374025, 2023). "The genetic study demonstrated that Tns2 was the disease-causing gene in the ICR-derived glomerulonephritis (ICGN) mouse line with a hereditary nephrotic syndrome (NS) and their symptoms were dedicated by mouse genetic backgrounds." (PMID 37374025, 2023). "Tensin 2 deficiency in ICGN mice leading to the nephrotic syndrome provides strong evidence that this pseudophosphatase may be an important target for renal failure." (PMID 34203203, 2021). "Interestingly, a distinct disease phenotype of partially treatment sensitive nephrotic syndrome (pTSNS) occurred in four of the five individuals with recessive TNS2 and in two of the four individuals with DLC1 mutations." (PMID 29773874, 2018). "A congenital nephrotic syndrome mouse model (ICGN mice) have an eight-nucleotide deletion in tensin 2, which triggers a frame shift that introduces a nonsense mutation." (PMID 34203203, 2021). "Since DLC1 is regulated by cyclic dependent kinase 20 (CDK20) and tensin-2 (TNS2), mutations in TNS2 and cyclin-dependent kinase 20 (CDK20) are also causative in some cases of nephrotic syndrome." (PMID 32708597, 2020). "For instance, Tns2 knockout mice, which develop nephrotic syndrome in a strain-dependent manner, present with proteinuria due to glomerular basement membrane abnormalities and subsequent podocyte foot process effacement as early as two weeks of age in the FVB/N background." (PMID 38674390, 2024).
diabetes (4 papers, 2016 to 2023). "While both B6 and 129T mice are resistant to Tns2 deficiency, B6 mice also exhibit lower albuminuria in hypertension or diabetes model than do 129 strains." (PMID 27230548, 2016). "Indeed, B6 mice appear to be resistant to various podocyte injuries caused not only by Tns2 deficiency but also by hypertension, diabetes, angiotensin II infusion, HIV-associated nephropathy (HIVAN), albumin overload, renal ablation or congenital nephron reduction." (PMID 27230548, 2016). "We identified novel targets including CLTC (clathrin heavy chain), TNS2, PLCG1 and NIFK (nucleolar protein interacting with the FHA domain of MKI67) for specific therapy of diabetes mellitus and obesity." (PMID 36837510, 2023). "Once the effects of Axl on glucose uptake and/or glucose metabolism are established, novel strategies may be devised to target the molecules involved in these pathways, e.g., TNS2 and IRS-1, to improve the treatment for PDAC and diabetes." (PMID 30419905, 2018).
lung carcinoma (4 papers, 2016 to 2025). "Analysis of TNS2 expression patterns in human cancer patients has indicated that TNS2 is rarely overexpressed in cancers and patients with low TNS2 expression are associated with poor relapse-free survival probabilities in breast and lung cancers." (PMID 27203214, 2016). "On the other hand, low expression of TNS2 was significantly associated with poor overall prognosis in seven lung cancer cohorts, two breast cancer cohorts and one bladder cancer group." (PMID 27203214, 2016). "In contrast, TNS2 overexpression reduces cell proliferation and survival of some cervical and lung cancer cells." (PMID 37510408, 2023). "According to other studies, reduced TNS2 expression is positively correlated with short relapse-free survival of breast and lung cancer patients." (PMID 33926026, 2021). "In addition, patients with low TNS2 expression showed poor relapse-free survival rates for breast and lung cancers." (PMID 27203214, 2016). "TNS2 shows promise as a diagnostic adjunct for discriminating GISTs from other gastric sarcomas, while TNS1 and TNS4 are increasingly incorporated into validated multi-gene signatures predicting survival and therapeutic response in bladder, colorectal, gastric, and lung cancers." (PMID 40906372, 2025). "In addition to the overall survival, patients' relapse-free survival probabilities of TNS2 expression in 3 lung cancer datasets (GSE50081, GSE41271, and GSE31210) and 1 breast cancer dataset (GSE1456_U133A) were available and analyzed by using the online survival analysis tools at PROGgeneV2." (PMID 27203214, 2016). "One lung cancer (GSE3210) and one breast cancer (GSE1456_U133A) datasets showed the significant correlation of low TNS2 expression with poor relapse-free survival." (PMID 27203214, 2016).
breast carcinoma (3 papers, 2015 to 2023). "In addition, poor relapse-free survival rates were associated with patents with lower TNS2 levels in one lung and one breast cancer cohorts." (PMID 27203214, 2016). "In addition, downregulation of TNS1, TNS2 or TNS3 reduces the invasiveness of ovarian and breast cancer cell lines by impairing integrin internalization and focal adhesion turnover." (PMID 37510408, 2023).
colorectal carcinoma (3 papers, 2016 to 2023). A malignant epithelial neoplasm that arises from the colon or rectum and invades through the muscularis mucosa into the submucosa. "Some of the identified phosphopeptides were derived from ISR2, BCAR, TNS2, SELH, CDC25b, and beta-catenin, concordant with the identification of phosphorylated ISR2, TNS2, and SELH peptides in the colorectal cancer immunopeptidome." (PMID 36291752, 2022).
pancreatic ductal adenocarcinoma (3 papers, 2018 to 2026). An infiltrating adenocarcinoma that arises from the epithelial cells of the pancreas. "TNS2 and TNS3 are not involved in the development of ductal pancreatic adenocarcinoma." (PMID 41923376, 2026).
renal failure (3 papers, 2016 to 2022). "This genetic background-dependent diversity indicates the presence of modifier genes that prevent renal failure induced by Tns2 deficiency." (PMID 27230548, 2016). "The effect caused by tensin 2 deletion in this model illustrates the protein's key role in normal renal function and suggests that this pseudophosphatase may be involved in renal failure." (PMID 36106167, 2022). "In addition, the severity of the renal failure caused by Tns2 deficiency is strongly influenced by murine genetic background." (PMID 27230548, 2016). "Tensin 2 is also a pseudophosphatase that has a critical role in diseases such as cancer and renal failure." (PMID 34203203, 2021). "Tensin 2 plays a critical role in renal failure and liver cancer." (PMID 36106167, 2022).
bladder cancer (2 papers, 2016 to 2025). "Our TWAS identified an additional gene, namely TENC1 (also known as C1TEN, C1-TEN, and TNS2), not mapping to the genome-wide statistically significant bladder cancer loci identified in the present or previous GWAS." (PMID 39898788, 2025).
colon cancer (2 papers, 2016 to 2018). "Several proteins have been found to interact with TNS2 through its C231 site of the PTPase domain; this C231 mutation may abolish the tumorigenicity of breast and colon cancer cells." (PMID 30419905, 2018). "Using public database analyses we found that TNS2 is down-regulated in head and neck, esophageal, breast, lung, liver, and colon cancer." (PMID 27203214, 2016).
gastric cancer (2 papers, 2021 to 2022). A primary or metastatic malignant neoplasm involving the stomach. "TNS1, TNS2 and TNS3 proteins expression was evaluated in 90 patients with gastric cancer by immunohistochemistry method." (PMID 33926026, 2021). "In contrast, positive expression of TNS2 and TNS3 was observed more frequently in moderately differentiated gastric cancer than in poorly or undifferentiated tumors." (PMID 33926026, 2021). "The expression of TNS1, TNS2 and TNS3 was examined immunohistochemically in 90 gastric cancer samples and 20 normal gastric tissues." (PMID 33926026, 2021). "Interestingly, TNS2 expression in gastric cancer did not correlate with sex, tumor localization, or metastases, unlike TNS2 expression in GIST in this study." (PMID 35804982, 2022).
hepatocellular carcinoma (2 papers, 2016 to 2022). A malignant tumor that arises from hepatocytes. "By analyzing human cancer expression profiles, we found TNS2 was down-regulated in a variety of cancers, including hepatocellular carcinoma (HCC) patients." (PMID 27203214, 2016). "The functional role of TNS2 remains unclear, as in some cancers, such as hepatocellular carcinoma, it has been shown to promote aggressive tumor behavior, but it has also been established to have tumor-suppressive properties and functions." (PMID 35804982, 2022).
sarcoma (2 papers, 2022 to 2025). A usually aggressive malignant neoplasm of the soft tissue or bone. "We investigated the role of TNS2 as a diagnostic biomarker by using immunohistochemistry in 176 GISTs and 521 other sarcomas." (PMID 35804982, 2022). "Comparative analysis of 148 GISTs versus other sarcomas and gastrointestinal primary tumors revealed markedly elevated TNS2 expression in GISTs, with 71.4% showing intermediate/strong staining compared to only 2.9% in other sarcomas." (PMID 40906372, 2025). "Here, we provide conclusive evidence that TNS2 is indeed a promising diagnostic marker for GIST, being specific to GIST among other sarcomas." (PMID 35804982, 2022). "A positive predictive value (PPV) and negative predictive value (NPV) to distinguish GISTs from other sarcomas based on TNS2 immunohistochemical expressions were calculated from the sarcoma screening series." (PMID 35804982, 2022). "TNS2 was highly expressed in GISTs (71.4% intermediate or strong expression) compared with other sarcomas (2.9% intermediate or strong expression)." (PMID 35804982, 2022). "The GIST series (n = 148) was stained for all three markers (TNS2, KIT, and DOG1), while the sarcoma screening series (n = 548) was only stained for TNS2." (PMID 35804982, 2022). "TNS2 mRNA expression is higher in GIST than in any other cancer, and is also overexpressed on the protein level compared with other sarcomas." (PMID 35804982, 2022). "In the present study, we found that 89% of gastric GISTs have intermediate to strong TNS2 expression, while 90% of non-GIST sarcomas examined were completely negative for TNS2 expression." (PMID 35804982, 2022). "A total of 70 GISTs (40%) showed strong TNS2 expression, whereas none of the other sarcoma types showed strong expression." (PMID 35804982, 2022). "The majority (89.8%) of other sarcomas were negative for TNS2, and intermediate to strong staining was only seen in 2.9% of samples." (PMID 35804982, 2022). "All 175 GISTs examined displayed TNS2 expression, while 468 (89.8%) of the 521 other sarcomas were completely negative for TNS2." (PMID 35804982, 2022).
cystic kidney disease (1 paper, 2025). A congenital or acquired kidney disorder characterized by the presence of renal cysts. "Seven genes (3%) had no entries in OMIM (DLG5 in renal ciliopathies and cystic kidney diseases; and 6 in the proteinuric kidney diseases [APOE, DLC1, FAT1, ITSN1, PODXL and TNS2]) and were excluded." (PMID 40303230, 2025).
cystic kidneys (1 paper, 2023). "Deficiencies in TNS1 or TNS2 result in CKD displaying cystic kidneys or NS, respectively." (PMID 37374025, 2023).
gastric tumors (1 paper, 2022). "TNS2 expression was found to be stronger in gastric tumors than in non-gastric tumors (p < 0.001, FH test) and in non-metastatic tumors than in metastatic tumors (p = 0.004, FH test)." (PMID 35804982, 2022).
gastrointestinal stromal tumor (1 paper, 2025). "Clinically, tensin dysregulation correlates with metastasis and poor prognosis: TNS2 serves as a diagnostic biomarker for gastrointestinal stromal tumors, aberrant TNS1/TNS3 expression predicts metastasis risk, and TNS4 is recurrently embedded in multi-gene prognostic signatures." (PMID 40906372, 2025). "TNS2 exhibits notable diagnostic specificity for gastrointestinal stromal tumors (GISTs)." (PMID 40906372, 2025).
heart failure (1 paper, 2024). Inability of the heart to pump blood at an adequate rate to meet tissue metabolic requirements.
lipoma (1 paper, 2022). A benign, usually painless, well-circumscribed lipomatous tumor composed of adipose tissue. "Additionally, future studies on the expression of TNS2 in other gastrointestinal malignancies, such as lipomas and schwannomas, could be beneficial to more accurately define the role of TNS2 as a diagnostic marker." (PMID 35804982, 2022).
metastatic tumors (1 paper, 2022). "The results provide conclusive evidence for the value of TNS2 as a sensitive and specific diagnostic biomarker for GIST, with stronger associations for gastric and non-metastatic tumors." (PMID 35804982, 2022).
ovarian carcinoma (1 paper, 2025). A malignant neoplasm originating from the surface ovarian epithelium. "Ectopic TNS2 expression inhibited HEK293 cell migration, whereas TNS2 knockdown impaired integrin internalization and decreased the invasiveness of Rab25-transfected A2780 ovarian cancer cells." (PMID 40906372, 2025).
ovarian tumors (1 paper, 2021). "Over-representation of negative TNS2 (B) and positive PLEC (C) was associated with the focal adhesion pathway; PLEC (D) expression was upregulated in ovarian tumors as compared to normal ovarian tissues, while TNS2 (E) expression was the opposite." (PMID 34419939, 2021).
pancreatic cancer (1 paper, 2018). "In this study, we examined the signaling effects of the TNS2 V2 isoform in pancreatic cancer cell lines." (PMID 30419905, 2018). "The TNS2 expression status of five pancreatic cancer cell lines was determined by Western blot analysis." (PMID 30419905, 2018). "Our results suggest that Axl binds to and phosphorylates TNS2 and is involved in glucose metabolism in human pancreatic cancer cells." (PMID 30419905, 2018). "In this study, we confirmed the relationship between TNS2 expression and the expression of Axl, IRS-1, PDK1 and Glut4 in pancreatic cancer patients." (PMID 30419905, 2018). "Moreover, we found a positive relationship between TNS2 expression and the expression of Axl, IRS-1, PDK1 and Glut4 in pancreatic cancer patients." (PMID 30419905, 2018). "Therefore, we further examined the correlation of TNS2 expression and expression of Axl, IRS-1, pyruvate dehydrogenase kinase 1 (PDK1) and glucose transporter type 4 (Glut4) in tissue of 33 patients with pancreatic cancer." (PMID 30419905, 2018).
renal cell cancer (1 paper, 2022). "In renal cell cancer, TNS2 was shown to not correlate with metastases to nearby lymph nodes or to infiltrate to blood and lymphatic vessels." (PMID 35804982, 2022).
schizophrenia (1 paper, 2017). A major psychotic disorder characterized by abnormalities in the perception or expression of reality. "For example, another gene identified here, TNS2 (TENC1), has previously been found to interact with schizophrenia risk gene DISC168 and is involved in the regulation of Akt, an important modulator of Wnt signaling." (PMID 29249829, 2017). "Among these, the four genes most strongly altered in schizophrenia were WFS1 (P = 1.8×10−7), angiotensinogen (AGT, P = 1.3×10−6), LRP4 (P = 2.7×10−6), and TNS2 (P = 9.3×10−4), all of which were increased in schizophrenia." (PMID 29249829, 2017).